IGFBP3 (insulin like growth factor binding protein 3)
Diseases named in the same sentence as IGFBP3 in open-access papers (continued):
Sharing a sentence is not in itself a finding about the gene and the disease.
tumor (continued). "The increased intra-tumoral expression of CD3 was significantly associated with decreased tumor weight only in BP3KO mice, suggesting that IGFBP-3 potentially has a novel role in suppressing T-cell infiltration into tumors." (PMID 27448965, 2016). "Aside from tumor cells themselves, components of the tumor microenvironment, such as endothelial cells and fibroblasts, also secrete IGFBP-3 and can contribute to overall tumor levels of IGFBP-3." (PMID 27448965, 2016). "It is important to reiterate that the influence of IGFBP-3 on tumor cell behaviour has been reported to be both cell-type and context-dependent, involving several signaling pathways." (PMID 27448965, 2016). "IGFBP-3 can exert pro-survival or proliferative as well as pro-apoptotic effects on tumor cells, and supports tumor growth in vitro by enhancing DNA damage repair and autophagy and by potentiating EGF receptor activation." (PMID 27448965, 2016). "The survival time predictions using the current clinical parameters only, such as age at diagnosis, Gleason score, PSA value and tumor stage, and clinical parameters supplemented with the expression levels of IGFBP3 and F3, were compared." (PMID 26731648, 2016). "As a predominantly secreted protein, IGFBP-3 plays important roles in several molecular mechanisms and signaling pathways that regulate cell survival or apoptosis, particularly in the case of tumor." (PMID 27978831, 2016). "The stimulatory effect of IGFBP-3 on tumor growth is consistent with the clinical observation that high levels of intra-tumoral IGFBP-3 are associated with poorer prognosis." (PMID 27448965, 2016). "IGFBP-3 is involved in the formation and function of blood vessels in both retinal and tumor models." (PMID 27448965, 2016). "IGFBP-3 immunoreactivity was assessed by a scoring system based on the percentage of positive tumor cells." (PMID 26370590, 2015). "Among the 87 specimens available for evaluation of tumor IGFBP3 staining, 65.5% (57/87) of them showed high (score 2, 3) IGFBP3 expression." (PMID 26540630, 2015). "Here, we observed that IGFBP-3 had favorable impact on the tumorigenicity of ESCC cells in nude mice by using an in vivo imaging system (IVIS) to monitor tumor growth treated with ionizing radiation (IR)." (PMID 26670461, 2015). "Downregulation of IGFBP-3 expression enhanced tumor growth, inhibited anti-proliferative and apoptotic activity and result in IR resistance in vivo." (PMID 26670461, 2015). "Patients with elevated protein level of IGFBP-3 in the tumor had an improved radiotherapy response and prolonged overall survival (P < 0.001)." (PMID 26370590, 2015). "Upregulation of IGFBP-3 expression strongly reduced tumor growth and improved radiosensitivity in vivo." (PMID 26670461, 2015). "IGFBP-3 regulates cell proliferation, has proapoptotic effects, and reduces tumor growth through both IGF-dependent and -independent mechanisms." (PMID 26670461, 2015). "In contrast, IGFBP3 has an activity of antioxidation, suppressing reactive oxygen species and promoting epithelial-to-mesenchymal transition and motility for tumor progression." (PMID 26540630, 2015). "The high expression levels of both EGFR and IGFBP-3 are seen in tumour tissue compared with normal tissue in case of oesophageal cancer." (PMID 25866791, 2015). "On the contrary, among the 83 specimens of non-tumor epithelia, only 16.9% (14/83) of them showed high expression of IGFBP3 (p < 0.001)." (PMID 26540630, 2015). "For example, IGFBP-3 has shown proapoptotic, antiproliferative, and antiangiogenic functions in in vitro tumour models." (PMID 25866791, 2015). "In HCC patients, reduced expression of IGFBP3 has been found to be significantly correlated with tumour size, histological differentiation, capsular invasion, portal venous invasion and poor survival." (PMID 25225571, 2014). "More in detail, Tumor Volume Inhibition percent (TVI%) in IGFBP-3-treated mice was respectively of 40,33 and 94,61% at 28 days post-tumor implant." (PMID 24905466, 2014).
tumor (continued). "In cancer studies, it has been shown that IGFBP3 functions as a tumor suppressor, and hypermethylation-mediated IGFBP3 gene silencing promotes cancer progression." (PMID 24964199, 2014). "In gene expression measurements of both IGFBP3 and F3, the primary and secondary tumor patterns provided results that were in agreement, and for these cases it was known that only a minor fraction of the tumor samples in fact contained stromal cells." (PMID 25296164, 2014). "Measurements of the gene signature in benign tissue revealed that IGFBP3 consistently provided similar values to those in the tumor tissue from the same patient, F3 remained similar but with larger variation, and VGLL3 was highly variable." (PMID 25296164, 2014). "Tumor growth was strongly inhibited already upon administering low doses of IGFBP-3, and completely arrested in 2 out of 8 cases already at lower doses, and in 3 out of 8 cases at higher doses." (PMID 24905466, 2014). "At sacrifice, tumor diameter was significantly lower (t-Test p<0.001) in IGFBP-3 (3±1,5 and 4.5±2 mm) in comparison to saline (9.0±3 mm) treated mice." (PMID 24905466, 2014). "Similar findings have been reported with Igfbp3 where it acts to suppress tumor cell growth but it promotes normal mammary epithelial cell growth." (PMID 24505323, 2014). "Exposure of A549 cells to celecoxib significantly elevated the levels of IGFBP-3 in tumor cell culture supernatants, even when the dose of celecoxib was very low (6.25 μmol)." (PMID 23833672, 2013). "To examine its contribution to tumor growth, we identified several shRNA constructs that suppressed IGFBP3 protein expression in VHL-/- cells." (PMID 24260413, 2013). "We found that the suppression of IGFBP3 very significantly increased the tumor growth, suggesting that it is another potent tumor-inhibitory HRG." (PMID 24260413, 2013). "In this study we examined the contribution of important HIF-responsive genes such as VEGF, CCND1, ANGPTL4, EGLN3, ENO2, GLUT1 and IGFBP3 to tumor growth in a xenograft model using immune-compromised nude mice." (PMID 24260413, 2013). "Results showed that the expression level of IGFBP3 in tumor tissues was significantly lower than that in adjacent tumor-free tissues (p<0.001)." (PMID 24386080, 2013). "Ibanez de Caceres and colleagues reported that a loss of insulin-like growth factor binding protein-3 (IGFBP-3) expression, mediated by promoter hypermethylation, resulted in a reduction of tumor cell sensitivity to cisplatin in NSCLC." (PMID 24130964, 2013). "We and others have revealed one common target gene IGFBP3, which has been reported to serve as a tumor suppressor." (PMID 24386080, 2013). "The complex balance between IGFs and IGFBP-3 determines the outcome for tumor cells between survival, growth or death." (PMID 23833672, 2013). "Surprisingly, depletion of GLUT1 or IGFBP3 significantly increased tumor growth, suggesting that they have tumor-inhibitory functions." (PMID 24260413, 2013). "In these instances, the IGFBP3 long-range interactions present in normal breast cells were maintained in the tumor cells, and additional interactions with the reciprocal breakpoints were formed due to rearrangements in the cancer cell line." (PMID 24019942, 2013). "IHC analysis of tumor samples showed that Akt and Erk1/2 phosphorylation was maintained at control levels in the trastuzumab-treated group, whereas IGFBP3 (alone or in combination with trastuzumab) reduced Akt and MAPK signaling." (PMID 22830017, 2012). "Adding 1 μg/ml recombinant human IGFBP3 to tumor cell lines resulted in comparable growth rates over time." (PMID 22401581, 2012). "Of these up-regulated genes, we further studied insulin-like growth factor binding protein 3 (IGFBP-3), since this gene is a well-established tumor-suppressive gene in PC." (PMID 22879989, 2012).
tumor (continued). "KGF also induced downregulation of a set of genes specifically upregulated in SCC cells compared to normal keratinocytes, including genes associated with tumor progression (MMP13, MATN2, CXCL10, and IGFBP3)." (PMID 22427941, 2012). "In summary, our findings support a regulatory role for FOXA1 in tumor proliferation via the regulation of IGFBP-3 expression in PC." (PMID 22879989, 2012). "We plotted baseline levels of IGF-1 or IGFBP-3, and maximum percent tumor reduction, time to progression, maximum proportional changes in neutrophil or platelet counts, AUC of ganitumab, minimum observed concentration, Cmax, or t1/2, z (data not shown)." (PMID 22810805, 2012). "Congruent with our assumption, high promoter hypermethylation frequencies of tumor suppressor genes, including IGFBP3, already serve as an indicator for a distinct subclass of advanced HCC in adults with a poor prognosis." (PMID 22401581, 2012). "The mRNA level of IGF-1, IGF-1R, IGF-2, IGF-2R, and IGFBP-3 was significantly higher in tumor and tumor-adjacent endometrium than that in control endometrium (p < 0.05)." (PMID 22720981, 2012). "In KYSE30 cell xenografts, Nimotuzumab combined with radiation led to significant tumor growth delay, compared with that of radiation alone (P=0.029), and also with IGFBP-3 up-regulation in tumor tissue." (PMID 23232108, 2012). "We further study the correlation of IGF-1, IGF-1R, IGF-2, IGF-2R, and IGFBP-3 mRNA expression with ERα and ERβ mRNA expression in tumor, tumor-adjacent and control endometria." (PMID 22720981, 2012). "We identified the tumor suppressor IGFBP-3 as a novel target of FOXA1, and showed that FOXA1 targeting of IGFBP-3 plays an essential role in regulating PC cell proliferation." (PMID 22879989, 2012). "We tested the expression of IGF-1, IGF-1R, IGF-2, IGF-2R, IGFBP-3, ERα and ERβ mRNA on 58 tumor tissue samples and 31 tumor-adjacent endometrial tissue samples from patients with EAC and 42 normal endometrial tissue samples, using RT-PCR." (PMID 22720981, 2012). "IGFBP-7, although has relatively low affinity toward IGF-1 and IGF-2, exerts a similar anti-tumor effect as its high affinity IGFBP counterpart IGFBP-3." (PMID 21729319, 2011). "ADM is also a hypoxia-inducible gene which plays an important role in tumor progression and angiogenesis while IGFBP3 is a pro-apoptotic gene induced by hypoxia." (PMID 21455298, 2011). "The association is not substantially modified by menopausal status at blood collection or by IGFBP3 concentrations, but seems to be confined to oestrogen-receptor-positive tumours." (PMID 20472501, 2010). "Taken together, this data suggests that IGFBP3 sensitizes GIST882 cells to the anti-tumor effects of imatinib." (PMID 19903356, 2009). "Dietary factors including sodium butyrate and retinoic acid induced IGFBP-3 in gut epithelial cells as well as protect against neoplasia." (PMID 18498652, 2008). "In those studies, IGFBP-3 was shown to exert direct, tumor-suppressive effects via IGF-independent inhibition of angiogenesis and both IGF-dependent and -independent induction of apoptosis." (PMID 19025658, 2008). "We assessed tumor-expression and circulating sera levels of IGFBP-3 and -4 using immunohistochemistry and ELISA assays." (PMID 19025658, 2008). "IGFBP3 expressions in both tumor and adjacent tissues were higher in patients who had proliferative benign tumors than in those who had non-proliferative benign tumors." (PMID 17210081, 2007). "Although the frequency and levels of GSTP1 methylation were significantly higher than IGFBP3 methylation, an unexpected finding was the concordance between methylation of both genes across all tumours and all but one HGPIN." (PMID 17453001, 2007).
tumor (continued). "In total, 7/37 (18.9%) of the hyperplastic prostates showed methylation of IGFBP3, a frequency significantly less than detected in the tumours (P<0.0001)." (PMID 17453001, 2007). "IGFBP3 methylation was only detected in HGPIN samples from patients whose adjacent tumour was also methylated." (PMID 17453001, 2007). "We found that IGFBP3 mRNA levels were substantially lower in cancer tissues than in tumor tissues from patients with BBD." (PMID 17210081, 2007). "The expression levels of IGFBP3 mRNA were substantially lower in tumor tissues from patients with cancer than those from patients with BBD (p < 0.001)." (PMID 17210081, 2007). "In patients with BBD, IGFBP3 mRNA levels were elevated in tumor tissues, particularly from patients with a proliferative BBD, compared with adjacent normal tissues." (PMID 17210081, 2007). "Methylation of IGFBP3 was only detected in those samples (both tumour and the majority of HGPIN) that demonstrated GSTP1 methylation." (PMID 17453001, 2007). "Among patients with BBD, IGFBP3 expression in both tumor and adjacent tissues was higher in patients who had proliferative tumors than those who had non-proliferative tumors." (PMID 17210081, 2007). "IGFBP3 expression in tumor tissues was significantly higher than that in their paired adjacent normal tissue among patients with BBD (p = 0.006)." (PMID 17210081, 2007). "This implies that hypermethylation of IGFBP3 occurs as an early event in prostate carcinogenesis and supports a clonal relation between the tumour and HGPIN lesion." (PMID 17453001, 2007). "The HER2 oncogene is known to upregulate IGFBP-3, and was upregulated on the in vivo array more than two-fold in 22 of 39 tumour samples." (PMID 16052224, 2005). "A comparison of categorical IGFBP-3 expression with ER-positive (quick-score 4–8) and ER-negative (quick-score 0–3) IDCs showed a trend (P = 0.06) with ER-negative tumours and HER-2-positive invasive tumours (P = 0.065)." (PMID 15642160, 2005). "Circulating levels of IGF-I and IGFBP-3 are relatively high, however (about 500–1000 times the concentration of insulin, for example), and it is very unlikely that increased synthesis of IGF-I or IGFBP-3 by tumours would substantially alter circulating levels." (PMID 14583772, 2003). "Although IGFBP3 was identified as a risk-associated gene of CRC, its linkage to NK cells, memory B cells, and Th cells suggests a potential role in innate immunity and anti-tumor surveillance." (PMID 40426943, 2025). "Heatmap analysis revealed a significant positive correlation between FTO and IGFBP3 mRNA levels (r = .4503) and this was confirmed by western blot analysis, which showed significantly elevated IGFBP3 protein levels in tumour tissues compared with adjacent normal lung tissues." (PMID 40621649, 2025). "In addition, spatial transcriptome analysis also confirmed that CD8+T cells around tumor cells with high IGFBP3 expression were significantly reduced." (PMID 40443651, 2025). "Furthermore, an incredible study in PDAC using high-resolution immunofluorescence demonstrated that through SEMA7A and ATP1A1 interactions, tumor cells promote fibroblast secretion of IGFBP-3." (PMID 41226289, 2025). "IGFBP-3 expression in pericytes positively regulates tumor cell proliferation and migration." (PMID 41226289, 2025). "The C2 IGFBP3+ tumor cell subtype discovery raises important questions for upcoming study." (PMID 41383633, 2025). "IGFBP-3 mediates antiproliferative and proapoptotic effects and acts as a tumour suppressor." (PMID 38969699, 2024). "IGFBP-3 might have tumor-suppressing or tumor-promoting effects depending on cell types, posttranslational modifications, and assay methods." (PMID 39272080, 2024). "Next, we investigated the tumor-promoting role of IGFBP3 in vivo." (PMID 38326861, 2024). "Additionally, a Violin plot revealed that with the increase in IGFBP3 expression, the tumor stage was later." (PMID 38463397, 2024).
tumor (continued). "One possible mechanism for IGFBP3 induction in TECs may be the hypoxic tumor microenvironment since it is a HIF-regulated gene." (PMID 39516665, 2024). "Importantly, in vivo experiments targeting IGFBP3 suppressed tumor growth and significantly prolonged the survival of mice." (PMID 38326861, 2024). "Additionally, knockdown of IGFBP3 attenuates tumor growth and significantly increases the survival rate in a mouse orthotopic tumor model." (PMID 38326861, 2024). "Furthermore, IGFBP-3 and its receptor have been reported to have anti-cancer and anti-metastatic effects, attenuating tumor progression." (PMID 38822233, 2024). "Based on the TCGA cohort, with progressing tumor stages, IGFBP3 gene expression increased." (PMID 37397026, 2023). "To identify candidate stroma-derived factors that might influence desmoid tumor cell proliferation, we treated mutant-only cultures with recombinant IGFBP3, PTX3, CCL2, CXCL12, and CHI3L1 in serum-free conditions." (PMID 37377751, 2023). "Indeed, 1α,25(OH)2D3 has been shown to induce antiproliferative genes such as CEBPA (CCAAT-α enhancer binding protein) and IGFBP3 (insulin-like growth factor binding protein 3) in tumour cells." (PMID 37299554, 2023). "Therefore, we identified three SASP-related genes (VGF, IGFBP3, and ANG), established a risk score, and uncovered detrimental and beneficial tumor subtypes based on these genes." (PMID 37624511, 2023). "However, there are also examples of miR-19a-3p itself acting as an oncogene, so if IGFBP-3 downregulation is involved in these effects, this would imply a tumor-suppressive role of IGFBP-3." (PMID 35597813, 2022). "Those related factors change during tumor therapy which might also contribute to the heterogeneity of IGF-1 or IGFBP-3 levels." (PMID 36425849, 2022). "Transfer of IGFBP-3 via (hypoxic) cancer-derived EVs might thus suppress immune infiltration into the tumor and, as such, stimulate tumor growth." (PMID 36010994, 2022). "Considering the negative regulation of PURα on the mRNA translation of IGFBP3 in the cytoplasm and the effect of IGFBP3 on tumor progression, we hypothesized that cytoplasmic PURα plays an oncogenic role by inhibiting the mRNA translation of IGFBP3 in ESCC." (PMID 35945453, 2022). "The anti-tumor effect of IGFBP3 regulates mitogenic and antiapoptotic effects." (PMID 35958518, 2022). "IGFBP-3 has been proven to play an important role in a variety of tumours." (PMID 35069971, 2022). "Decreased CDKN1A has been found in multiple tumor cells, and several studies have shown that IGFBP3 could effectively inhibit the malignant behaviors of cancer cells." (PMID 35340229, 2022). "Compared with the control group, the xenograft tumours from mice treated with CVB exhibited an evident decrease in the levels of IGFBP3, p-AKT, p-STAT3, p-ERK, p-JNK, p-P38, Bcl-2, Snail, and Vimentin, while the levels of cleaved Caspase 3 and E-cadherin were increased." (PMID 34512163, 2021). "Several lines of evidence suggest that IGFBP‐3 acts as a potential tumor suppressor gene." (PMID 34485840, 2021). "However, the levels of nuclear NF-κB signal were higher in irradiated IGFBP3-expressing tumor cells (n = 60; 5.967 ± 0.857 per field) than in those in control sections (n = 60; 4.3 ± 0.4287 per field; p = 0.0846)." (PMID 33712045, 2021).